IL15 (interleukin 15)
Diseases named in the same sentence as IL15 in open-access papers (continued):
Sharing a sentence is not in itself a finding about the gene and the disease.
tumor (continued). "ALT-803 (N-803) is an IL-15 superagonist and reduces tumor burden by promoting the proliferation and activation of NK cells and CD8+ T cells." (PMID 36439125, 2022). "Several recent studies have revealed the superiority of IL-7/IL-15 over IL-2 in ex vivo expanding human naïve or tumor-experienced CD8+ T cells as well as CAR-T cells." (PMID 36394017, 2022). "A crucial role for IL-15 was demonstrated by the ability of anti-IL-15 monoclonal antibody treatment to alleviate ONP-302-induced delay of tumor growth." (PMID 36059473, 2022). "The potentiation of anti-tumor efficacy of monoclonal therapeutic antibodies by IL-15 or IL-15-based agonists has also been observed in mouse models in vivo." (PMID 36300122, 2022). "The data in this paper demonstrate that PD-L siRNA IL-15 DCs are capable of stimulating tumor-antigen T cells, even when PD-1 is overexpressed." (PMID 35250967, 2022). "This supported the notion that the anti-tumor efficacy mediated by the combination of IL-15 and monoclonal antibodies was predominantly dependent on the ADCC." (PMID 36300122, 2022). "CISH is a key negative regulator of IL-15 signaling in NK cells, and it inhibits anti-tumor activity of human NK cell." (PMID 36601109, 2022). "CAR-T cells that were exposed to IL-2 and IL-15 secreted more proinflammatory cytokines and presented stronger tumor-lysis ability in vitro." (PMID 36172343, 2022). "Therapies boosting NK cell activity like IL-15 superagonists, or engineered NK cell engagers are therefore promising strategies to sustain NK cell-mediated maintenance of tumor dormancy." (PMID 35832538, 2022). "Anti-CD16 x IL-15 x anti-CD33 TriKE played an anti-tumor role through eliciting NK cell functions in mouse models of tumors, and its efficacy was reported in a terminated clinical trial (NCT03214666)." (PMID 36246629, 2022). "This trial was based on the preclinical observation that NK cell activation with artificial IL-15Rα- and 4-1BBL-expressing antigen-presenting cells and soluble IL-15 leads to increased expression of activating receptors and enhanced tumor killing." (PMID 36348457, 2022). "Recently, to further boost the anti-tumor effect of IL-15-secreting CAR NK cells, investigators knocked out their CISH gene, which encodes the immune checkpoint protein, cytokine-inducible Src homology 2-containing protein (CIS)." (PMID 36428748, 2022). "These outcomes demonstrate that the combined adjuvant IL-15 improved the anti-tumor efficacy of CAR-T therapy." (PMID 36167591, 2022). "HSC‐engrafted NSG‐Tg(Hu‐IL15) mice that were treated with the NKp46 depleting antibody showed increased tumor growth kinetics as compared to isotype treated HSC‐engrafted NSG‐Tg(Hu‐IL15) mice." (PMID 35959876, 2022). "We comprehensively investigated the different expression levels of IL-15 in tumor and normal control tissues by using The Cancer Genome Atlas (TCGA), Genotype-Tissue Expression (GTEX), and tumor-related databases." (PMID 36467072, 2022). "A TRiKE CAM1615HER2, which contains a VHH targeting CD16a, an scFv for HER2 and IL-15, shows an increase in NK cell proliferation and activation in vitro and tumor clearance in vivo." (PMID 35720368, 2022). "ALT-803 increases the proliferation and activation of NK cells and CD8+ T cells by serving as a superagonist of IL-15, leading to a reduction of tumor burden." (PMID 36439125, 2022). "Studies have shown anti-tumor benefits for using IL-15 as well as IL-7 in culture or IL-15 genetically engineered into T cells with CAR synchronously." (PMID 36167591, 2022).
tumor (continued). "We also show that NK cells generated in HSC‐engrafted NSG‐Tg(Hu‐IL15) mice infiltrated the tumor microenvironment at a significantly higher level than in tumor‐bearing NSG non‐transgenic mice." (PMID 35959876, 2022). "Ultimately designed to induce a durable tumor-specific immune response, PD-L silenced IL-15 DCs were capable of rescuing antigen-specific cytotoxic T cells from PD-1-mediated inhibition." (PMID 35250967, 2022). "It reinforced our confidence in the usage of IL-15 pre-conditioned patient-derived γδT cells in an autologous adoptive transfer setting for tumor eradication." (PMID 35351861, 2022). "The anti-tumor activity of IL-15–expressing CAR T cells is mainly thought to derive from cell-autonomous effects and their effects on locally colonized non-engineered T cells." (PMID 36059449, 2022). "αβTCR/CD56-depleted OKT-3/IL-15-stimulated Vδ1 cells were highly tumor-reactive in their own right and amenable to transduction to high efficiency with a second generation B7H3-28ζ CAR using standard retroviral protocols." (PMID 35711450, 2022). "In our study, by mimicking the in vivo tumor microenvironment, we depleted the IL-15 after the 14-day cell expansion and found the patient-derived γδT cells possessed a much stronger anti-apoptotic ability in the following 96 h culture." (PMID 35351861, 2022). "They demonstrated sustained in vitro tumor cell killing by γδ CAR-iT-cells in the presence of IL-15, with markedly less IFN-γ and other inflammatory cytokines being produced compared to conventional αβ CAR-T-cells, potentially resulting in lower risk of CRS." (PMID 35784326, 2022). "Intratumor delivery of an mRNA-encoding cytokine mixture composed of IL12, IFN-α, GM-CSF, IL15, IL12, IL23, IL36, and OX40L promoted antitumor immunity and tumor regression in preclinical tumor models and clinical trials." (PMID 35715953, 2022). "A luciferase-labeled AML cell line (HL60-luci+) was intravenously injected into B-NDG hIL15 mice (NOD.CB17-PrkdcscidIl2rgtm1Il15tm1(IL15)/Bcgen background) for the establishment of human AML tumor-bearing animals." (PMID 36344493, 2022). "For example, the co-delivery of IL-15 and anti-β-catenin siRNAs with NPs can significantly improve anti-tumor immunity to inhibit tumor growth." (PMID 36015256, 2022). "Initial studies demonstrated that deletion of CISH in mice leads to increased sensitivity to IL-15, enhanced metabolism and improved anti-tumor activity of NK cells." (PMID 35185932, 2022). "We boldly believed that γδT cells in NB patients bore a tolerance to the extremely low level of IL-15 within the tumor microenvironment." (PMID 35351861, 2022). "The use of cytokines derived from the IL-2 family, such as interleukin IL-2, IL-7, IL-15, and IL-21, to stimulate the anti-tumor response is prevailing in the field of immunotherapy." (PMID 36275766, 2022). "Cytokine-induced memory-like NK cells were first described in a murine model by activating NK cells with IL-12, IL-15, and IL-18, amplifying their antitumor response, with a significant decrease in tumor burden and enhanced survival." (PMID 35954502, 2022). "IVIS images of mice bearing U87-derived tumors showed that tumor size was significantly decreased in the Ad5-Ki67/IL-15 plus GA-MSCs group compared with the GA-MSCs alone, especially 6 days after the virus injection." (PMID 35765095, 2022). "We and others have engineered oncolytic vaccinia viruses (VVs) expressing recombinant IL-2, IL-12, IL-15, IL-21, IL-23, and IL-36γ for improved efficacy and safety in multiple tumor models." (PMID 36221123, 2022).
tumor (continued). "Knocking out the CISH gene deletes the cytokine-inducible Src homology 2-containing (CIS) protein, a negative regulator of IL-15 signaling, which increases the cell’s metabolic activity and subsequent anti-tumor activity." (PMID 35565395, 2022). "Nevertheless, in another study, rBCG::IL-15 administration was shown to significantly prolong the survival of mice inoculated with bladder tumor cells and suppress tumor growth compared to mice treated with pBCG." (PMID 35632582, 2022). "In our investigation, we explored the use of three cytokines, TNFα, IL12 and IL15, all of which involve cell‐mediated tumour killing and provide promising results when TPA is used as a delivery method." (PMID 35758207, 2022). "Results consistently show that IL15-armored CAR T cells exhibit potent anti-tumor efficacy and enhanced persistence in vivo." (PMID 35806311, 2022). "Various studies have coexpressed IL-15 with oncolytic viruses to utilise the anti-tumour activity of this important cytokine." (PMID 34888493, 2021). "IL15 therapy has been demonstrated to attenuate tumor growth and improve survival rates in murine tumor models." (PMID 33918641, 2021). "Strategies to stimulate anti-tumor immune responses include treatment with cytokines such as IL-2, IL-15 and IFN-α, which have been shown to augment the efficacy of immune cells in vitro and in vivo." (PMID 34681717, 2021). "A single intraperitoneal injection of IL-15/IL-15Rα vector at low dose results in expansion of NK cell in adipose tissue and enhanced NK activity in tumor-bearing animals leading to survival benefit." (PMID 34394087, 2021). "More importantly, analysis of the endogenous immune infiltrate of tumours showed increased NK cell activation and reduced numbers of M2-like macrophages, suggesting the IL-15-secreting CAR T cells are able to disrupt and reprogram the TME." (PMID 34885108, 2021). "Olaparib did not induce a significant increase in PD-L1 expression in DU145 cells, but it can enhance the tumor lysis promoted by high-affinity NK cells or NK cells treated with an IL-15/IL-15 receptor-α superagonists." (PMID 34830179, 2021). "The relevance of IL-15 in anti-tumor immune response, CAR-T cell activation and differentiation into persisting T cell subsets is increasingly recognized." (PMID 34712233, 2021). "More importantly, the administration of IL‐15 in combination with ICIs prolonged the survival of tumour‐bearing mice." (PMID 34337889, 2021). "Liu and coworkers showed efficient iC9/CAR.19/IL-15 cell killing of CD19-expressing tumor cell lines in vitro and improved clinical outcome in a xenograft Raji lymphoma murine model." (PMID 34025641, 2021). "Combined treatment with interleukin-15 stimulation and immune checkpoint inhibition resulted in complete or partial tumor response in this model." (PMID 34081628, 2021). "In summary, these results indicate that high IL-15/IL-15Rα tumor abundance three days following vvDD-IL15/Rα treatment correlates with a cytotoxic CD8+ T cell immune response." (PMID 33679747, 2021). "The expression of the EWSR1-WT1, a fusion protein containing sections of EWSR1 and WT1 transcription factor, in proliferative small round cell tumors can induce the expression of IL-2 and IL-15, which are related to the proliferation of these tumor cells." (PMID 34124041, 2021). "Previous in vitro studies have reported that IL-15 activates NK and T cells and mediates anti-tumor immune responses." (PMID 33912464, 2021). "This suggests that IL-15/IL-15Rα expression had a differential effect on CD8+ T cells recognizing tumor." (PMID 33679747, 2021). "It was also shown that splenocytes from the mice injected with the IL-15:IL-15Rα-B16F10-OVA vaccine enhanced tumor antigen (OVA)-specific cytotoxicity against both B16F10-OVA and E.G7-OVA when they were stimulated with an OVA peptide in vitro." (PMID 34439192, 2021). "In this study, we also found that IL-15 has a significant effect on tumor shrinkage and prolonging survival in mice." (PMID 33912464, 2021).
tumor (continued). "IL-15 can be used for the ex vivo generation and expansion of tumor-specific lymphocytes, as well as for the in vivo support of the transferred cells." (PMID 33671252, 2021). "The studies concerning IL-15 so far have already focused on its role concerning tumor genesis and its effect on proliferation, invasion, and metastasis production." (PMID 32929618, 2021). "CAR T cells releasing IL-12, IL15, and IL-18 have been studied in preclinical models, increasing efficacy even in advanced tumours." (PMID 34831165, 2021). "Patients with a G3 tumor, who died in the follow-up period, showed considerably increased IL-15 values, in contrast to the significantly decreased IL-15 levels in patients with G3 tumor with favourable OS and DFS and were living at follow-up." (PMID 32929618, 2021). "Immunization with the BacMam-based IL-15:IL-15Rα cancer vaccine significantly delayed tumor growth by stimulating robust antitumor immune responses in tumor antigen-specific CD8+ T cells and NK cells while simultaneously attenuating Foxp3+ Treg cells." (PMID 34439192, 2021). "We also show that the effector potential of endogenous intraperitoneal T cells can be exploited and redirected toward tumor antigens by IL15/Rα-armed oncolytic vaccinia virus." (PMID 33679747, 2021). "We have therefore performed another experiment in thick, three-dimensional collagen gels, this time comparing a pure NK-system, a mixed NK-K562 system (wild-type tumor cells), and a mixed NK-K652/IL15 system (IL-15-secreting tumor cells)." (PMID 34294808, 2021). "In a syngeneic pancreatic tumor mouse model, IL15-hUCBMSCs inhibited tumor growth and increased survival of tumor-bearing mice." (PMID 33849537, 2021). "Their results show that the combination therapy of IL-15 after NIR-PIT inhibited tumour growth, prolonged survival, and increased tumour infiltrating CD8+ T cells more efficiently than NIR-PIT alone." (PMID 34200194, 2021). "Recent studies, carried out on animal tumor models, show that different cytokines, including GM-CSF, IL-7, IL-12, IL-15, IL-18 and IL-21, are also able to limit tumor growth." (PMID 34208413, 2021). "The 3D tumors were co-cultured with PBMCs from HLA-A2POS donors in the presence of interleukin (IL)-15 to stimulate immune cell-mediated tumor rejection." (PMID 34485603, 2021). "Another recent study used retroviral vector systems that ectopically expressed iC9/CAR.19/IL15 to generate CAR-CD19-NK cells from cord blood that persisted for a long time in the tumor microenvironment." (PMID 34925314, 2021). "After isolation of AH1-specific T cells from secondary lymphoid organs and tumor, we incubated cell samples in complete medium supplemented with high-dose IL15 and let them rest for five days." (PMID 33796916, 2021). "Both IL-10 and IL-15 have significant effects on tumor volume shrinkage as well as on prolonging mice survival." (PMID 33912464, 2021). "Considering the reduced number of NK cells and suppressed effector functions of tumor-infiltrating NK cells in cKO mice, we wondered if METTL3-deficient NK cells were defective in their response to IL-15." (PMID 34535671, 2021). "The combination of cetuximab with IL-15, an NK cell-activating cytokine, improved tumor cell killing by NK cells (grey bars)." (PMID 34681717, 2021). "The addition of IL-15 to PD-1 blockade completely abrogated tumor escape from ICI, leading to profound, prolonged tumor regression." (PMID 34081628, 2021). "Interleukin 15 was upregulated in AAGL-treated tumor-bearing mouse livers; this cytokine plays a critical role in the survival, maturation, proliferation, and activation of NK cells." (PMID 33710817, 2021). "According to reports, the CAR-T cell-modified TSCM was cocultured with IL-2, IL-7 or IL-15 and then injected intravenously into tumor-bearing mice." (PMID 34604060, 2021).
tumor (continued). "By day 14 post-treatment, both the 5 and 10 μg doses of cyto-IL-15 treatments significantly delayed tumor growth in comparison with vehicle by 42% (p < 0.01) and 50% (p < 0.001) respectively." (PMID 34778376, 2021). "These IL-15 producing mice are useful tools for the assessment of tumor models and combination immunotherapies involving NK cells." (PMID 33968039, 2021). "Use of cytokines like IL-2, IL-15, IL-12, IL-21 and IL-18 is considered a promising approach to induction of more efficient NK cell activation at tumor sites, while IL-15 and IL-21 can enhance NK cell cytotoxicity." (PMID 34177887, 2021). "Accordingly, a continuous and local action of IL-15 in the tumor microenvironment would be fundamental to counteracting GBM growth and progression." (PMID 34552593, 2021). "On the other hand, we observed a slight decline in the killing capacity of PBNK cells towards different tumor cell lines in the sixth week of expansion, most likely due to prolonged exposure to IL-15 that was reported to entail NK cell exhaustion." (PMID 33919155, 2021). "Elevated serum concentrations of IL-15 significantly correlate with patients diagnosed with Grade 3 tumor and worse OS." (PMID 32929618, 2021). "The addition of IL-15 to PD-1 blockade completely abrogated tumor escape from ICI, resulting in a powerful additive therapeutic effect capable of tumor eradication." (PMID 34025641, 2021). "We would therefore predict a potent anti-tumor response in-vivo with the IL-15/ADU-S100 combination." (PMID 33777767, 2021). "Several preclinical studies have shown that IL-15 promotes tumor infiltration of both lymphocytes and dendritic cells, through the induction of several cytokines, and supports the proliferation, survival, and cytotoxic activity of both CD8+ T and NK cells." (PMID 33671252, 2021). "The pattern of interactions found for donor 1 points to a scenario where NK immune cells are unable to sense and approach K562 tumor cells from afar, unless the tumor cells are manipulated to emit a traceable chemo-attractant, such as IL-15." (PMID 34294808, 2021). "Preclinical animal studies have supported their anti-tumor activity, suggesting IL-15 as a general method to convert “cold” tumors into “hot”, by promoting tumor lymphocyte infiltration." (PMID 33671252, 2021). "In IBD-associated cancer, it has been proposed that NK cells participate in anti-tumor immunity through IL-15 stimulation produced by CD11c+ DCs." (PMID 34884543, 2021). "Preclinical studies showed IL-15 induced prolonged expansion and activation of NK cells, resulting in tumor regression, decreased metastasis, and increased survival in a mouse model of lung adenocarcinoma." (PMID 34768814, 2021). "The expression of IL-15 has been described as a protective factor in tumor genesis and against tumor progression in certain publications, but in advanced solid cancers IL-15 expression acts contrarily thus contributing to disease progression." (PMID 32929618, 2021). "sch rhIL-15, hetIL-15, and IL-15:IL-15Rα fusion agonists were also all shown to have anti-cancer activity in several mouse tumor models." (PMID 33671252, 2021). "Specifically, AOM/DSS-treated mice that deleted IL-15 showed reduced survival and higher tumor incidence." (PMID 34884543, 2021). "Adoptive transfer of NK cells with ‘memory-like status’ was induced when exposed to a combination of cytokines such as IL-12, IL-15, and IL-18, and this has been proposed to enhance tumor immunity." (PMID 34439191, 2021). "IL-15 is known to prime T lymphocytes and NK cells when secreted by DCs and to then stimulate anti-tumor immune responses." (PMID 32929618, 2021). "Interleukin-15 (IL-15), a cytokine discovered in 1994, supports the homeostasis of cytotoxic immune cells and shows promise as an anti-tumor agent." (PMID 33671252, 2021). "IL-15 in in vitro and in vivo studies has been proven to increase the tumor volume as a consequence of inflammation and lipid mobilization." (PMID 32929618, 2021).